NFATC1 (nuclear factor of activated T cells 1)
Diseases named in the same sentence as NFATC1 in open-access papers (continued):
Sharing a sentence is not in itself a finding about the gene and the disease.
ameloblastoma (1 paper, 2022). The most common odontogenic tumor, arising from the epithelial component of the embryonic tooth and usually affecting the molar-ramus region of the mandible or maxilla. "In conclusion, Cav1.2 regulates the NFATc1 nuclear translocation to enhance ameloblastoma cell proliferation." (PMID 36057617, 2022).
aortic stenosis (1 paper, 2012). Aortic valve stenosis is a aortic valve disease caused by the incomplete opening of the aortic valve. "GATA5 was previously shown to be a strong partner of NFATC1 and its recent inactivation in mice did show that the embryos develop aortic stenosis one of the most frequent valve abnormalities." (PMID 23226213, 2012).
atrioventricular septal defect (1 paper, 2024). "NFATC1 coordinates the development of valve endocardial cells necessary for heart valve formation, and missense mutations in NFATC1 are associated with atrioventricular septal defect." (PMID 38886689, 2024).
autoimmune disorders (1 paper, 2025). "The interplay between NFATc1 and NFATc2 ensures a balanced immune response, preventing excessive activation that could lead to autoimmunity." (PMID 40688507, 2025).
B cell lymphopenia (1 paper, 2019). "The serious defects in early B cell differentiation in mice lacking NFATc1 activity in the hematopoietic system led to severe B cell lymphopenia, which further underscores the critical necessityof NFATc1 in facilitating B cell development." (PMID 29907883, 2019). "The severe B cell lymphopenia observed in the absence of NFATc1 activity was not present in mice that were deficient in NFATc2, NFATc3, or both." (PMID 29907883, 2019).
bladder tumor (1 paper, 2015). "In the present study, we demonstrate that NFATc1 inactivation via NFATc1-siRNA as well as CsA and FK506 results in bladder tumor regression." (PMID 25638160, 2015).
bladder urothelial carcinoma (1 paper, 2020). "Drugs targeting NFATC1 have been shown to inhibit the growth of bladder urothelial carcinoma." (PMID 32420368, 2020). "Also, the expression of NFATC1 and STAT1 are associated with PD-L1 in bladder urothelial carcinoma." (PMID 32420368, 2020).
bone cancer (1 paper, 2025). A primary or metastatic malignant neoplasm affecting the bone or articular cartilage. "This study aimed to test the hypothesis that nuclear factor of activated T cells 1 (NFAT1) signaling contributes to bone cancer pain by regulating interleukin (IL)‐18 expression in spinal microglia." (PMID 39957627, 2025).
bone metabolism disorders (1 paper, 2025). "Additionally, it can stimulate osteoclast differentiation and bone resorption capacity by facilitating Smad2-dependent NFATc1 nuclear translocation and PI3K/AKT/AP-1-mediated pro-inflammatory factor expression pathways, thereby contributing to bone metabolism disorders." (PMID 40136413, 2025).
breast tumors (1 paper, 2025). "Expression of NFATC1, a member of a family of transcription factors that regulate the immune system, is down-regulated in early-recurrent breast tumors." (PMID 39888956, 2025).
chronic kidney disease (1 paper, 2020). Impairment of the renal function secondary to chronic kidney damage persisting for three or more months. "Indoxyl sulfate (IS) is a chronic kidney disease (CKD)-specific renal osteodystrophy metabolite that affects the nuclear factor of activated T-cells, cytoplasmic 1 (NFATc1), a transcription factor promoting osteoclastogenesis." (PMID 32429048, 2020).
chronic tonsillitis (1 paper, 2018). "Similar results were obtained by α-NFATc1/αA staining of human tonsils from patients with chronic tonsillitis showing the nuclear expression of NFATc1/α in numerous GC cells." (PMID 29416540, 2018).
clear cell renal cell carcinoma (1 paper, 2020). "In addition, overexpression of TRPC6 in turn resulted in the nuclear translocation of NFAT (D1, D2 and E), suggesting this feedback loop between NFATc1 and TRPC6 exists in tubular cells in DN, like in podocytes, cardiomyocytes and clear cell renal cell carcinoma (ccRCC) cells." (PMID 32779844, 2020).
coronary heart disease (1 paper, 2021). "Thus, human NFATc1 is an active index of unstable plaques that can be used to evaluate the risk of coronary heart disease and further predict the occurrence of acute coronary events." (PMID 33791348, 2021). "The NFATc1 level is significantly higher in patients with coronary heart disease patients than in the control group, and the NFATc1 level in the unstable plaque group is higher than in the stable plaque group." (PMID 33791348, 2021).
disc degeneration (1 paper, 2024). "The percentage of NFATc1-positive cells were significantly higher in IVD samples showing a higher level of degeneration, suggesting that NFATc1 expression correlates with disc degeneration." (PMID 38638530, 2024).
endothelial dysfunction (1 paper, 2022). In vascular diseases, endothelial dysfunction is a systemic pathological state of the endothelium (the inner lining of blood vessels) and can be broadly defined as an imbalance between vasodilating and vasoconstricting substances produced by (or acting on) the endothelium. "Our results suggest that Orai1 and the downstream calmodulin/calcineurin/NFATC1/COL1A1 signaling pathway may play an important role in PTH-induced endothelial dysfunction and may be key potential therapeutic targets for preventing or treating SHPT-induced CVD." (PMID 35369318, 2022).
follicular lymphoma of the (1 paper, 2019). "To tackle the follicular nature of CD4+ T cells in the lymphoid aggregates, we performed IF stainings of CD4, CXCR5 together with NFATc1, again after having established detection on tonsils, follicular lymphoma of the spinal cord, and PCNSL of the brain." (PMID 32010141, 2019).
gastric lymphoma (1 paper, 2024). An extranodal lymphoma that arises from the stomach with the bulk of the mass located in the stomach. "Further investigations into the molecular mechanisms underlying the cooperative participation of CagA and NFATc1 in the pathogenesis of HPE-responsive gastric lymphoma are warranted." (PMID 39558403, 2024).
gastric MALT lymphoma (1 paper, 2024). "We further found that nuclear NFATc1 expression was significantly higher in HPE-responsive than in HPE-irresponsive MALT lymphoma of the stomach and was significantly associated with the expression of CagA." (PMID 39558403, 2024). "Our findings indicated that CagA and NFATc1 cooperatively participate in the lymphomagenesis of HPE-responsive gastric MALT lymphoma." (PMID 39558403, 2024). "This study identified the cooperative contribution of CagA and NFATc1 in the HPE-responsive pathogenesis of gastric MALT lymphoma." (PMID 39558403, 2024). "Our aim was to clarify whether, in addition to CagA, the nuclear localization of NFATc1 is involved in the pathogenesis of HPE-responsive gastric MALT lymphoma." (PMID 39558403, 2024). "In addition, among these HPE-responsive gastric MALT lymphomas, nuclear localization of NFATc1 was downregulated in post-HPE gastric biopsy samples." (PMID 39558403, 2024). "Multivariate analysis identified the presence of CagA (p < 0.001) as an independent marker for predicting HPE responsiveness in gastric MALT lymphoma, and nuclear localization of NFATc1 (p = 0.053) showed a non-significant association with HPE responsiveness in gastric MALT lymphoma." (PMID 39558403, 2024). "When CagA and NFATc1 were used as single markers to predict HPE responsiveness in gastric MALT lymphoma, the positive predictive values (PPV) for CagA and NFATc1 were 87.0% and 84.3%, respectively, and the specificity values for CagA and NFATc1 were 78.1% and 75.0%, respectively." (PMID 39558403, 2024).
glaucoma (1 paper, 2017). Increased pressure in the eyeball due to obstruction of the outflow of aqueous humor. "We unravel by WES a novel mutation in FOXC1 behind the ocular basic phenotype, and we propose a digenic model for the glaucoma phenotype along a mutation in the DPT gene and another digenic model for CHD involving yet a novel mutation in NFATC1." (PMID 28979898, 2017).
gout (1 paper, 2023). A condition characterized by painful swelling of the joints, which is caused by deposition of urate crystals. "Activation of NFATc1, c-JUN, and TNF receptor-associated factor-6 (TRAF6) downstream of the RANK-RANKL signal pathway has also been regarded as a crucial step for formation in osteoclast-like cells in the pathogenic mechanism of gout." (PMID 36986544, 2023).
Hyperinsulinemia (1 paper, 2021). An increased concentration of insulin in the blood. "NFATc1 overexpression increases VSMC migration and proliferation due to hyperinsulinemia." (PMID 33791348, 2021).
insulinomas (1 paper, 2020). "This suggests that NFATC1 may serve as an alternate driver of INS/IGF2 expression in insulinomas, possibly facilitated by looping from the SYT8/TNNI2 locus." (PMID 33060578, 2020). "Interestingly, NFATC1 is overexpressed by a log2-fold factor of 3 in insulinomas as compared to normal beta cells." (PMID 33060578, 2020).
joint effusion (1 paper, 2016). "Of note is the association of higher joint effusion grades with higher expression levels ofNFATC1 (nuclear factor of activated T cells 1)." (PMID 27134727, 2016).
kidney transplant (1 paper, 2018). A surgical procedure in which one or both kidneys from a donor are implanted into a recipient. "In conclusion, measuring NFATc1 amplification is a direct tool for monitoring biological effects of tacrolimus on T cells in whole blood samples of kidney transplant recipients." (PMID 30036394, 2018).
left ventricular hypertrophy (1 paper, 2024). Enlargement of the LEFT VENTRICLE of the heart. "Consistent with this, our previous studies have shown that children with bicuspid aortic valve (BAV) overexpress a nuclear factor of the activated T-cells 1 (NFATC1) gene, the key transcriptional activator, which correlates with the left ventricular hypertrophy." (PMID 38672493, 2024).
Listeria infection (1 paper, 2017). "These cells have reduced cytotoxicity against tumor cells, and mice with NFATc1-deficient T cells are defective in controlling Listeria infection." (PMID 28894104, 2017). "In our Listeria infection assays, we observed a slight increase in the number of Nfatc1−/− TCM, compared to WT cells, and a decrease of Nfatc1−/− TEM cells." (PMID 28894104, 2017).
liver cirrhosis (1 paper, 2018). "We found that low expression of NFATc1 in HCC was significantly associated with larger tumor size, advanced TNM stage, higher serum AFP levels, and liver cirrhosis." (PMID 30085405, 2018). "Our results demonstrated that low expression of NFATc1 was correlated with larger tumor size (P = 0.020), advanced TNM stage (P = 0.001), higher serum AFP levels (P = 0.021), and liver cirrhosis (P = 0.033)." (PMID 30085405, 2018). "Low expression of NFATc1 was correlated with larger tumor size, advanced tumor‐node‐metastasis (TNM) stage, high serum AFP level, and liver cirrhosis." (PMID 30085405, 2018).
liver fibrosis (1 paper, 2019). "The association between NFATc1 and Jnk expression and the degree of liver fibrosis was also assessed by correlation analysis." (PMID 30871618, 2019). "As a result, PI of NFATc1 and pJnk went up sharply along with the progression of liver fibrosis/inflammation status (P < 0.05, respectively)." (PMID 30871618, 2019). "With the progression of liver fibrosis, the expression of NFATc1 and pJnk in liver tissue increased." (PMID 30871618, 2019). "Most importantly, protein expressions of NFATc1 and pJnk have positive correlations with liver fibrosis scores in HBV-infected patients." (PMID 30871618, 2019). "Therefore, NFATc1 and Jnk protein expression also rose as liver fibrosis and inflammation progress." (PMID 30871618, 2019). "Finally, both NFATc1 and pJnk protein expressions had positive correlations with liver fibrosis score, proving the involvement of Wnt 5a/NFATc1 and Wnt 5a/Jnk pathways in HBV-induced liver fibrosis." (PMID 30871618, 2019).
lung fibrosis (1 paper, 2022). "In support of its profibrotic properties, a previous report showed that inhibition of NFATc1 by tacrolimus in mice exposed to bleomycin inhibited lung fibrosis progression." (PMID 35167499, 2022). "Although NFATc1 is expressed in mesenchymal cells, its role in fibroblast activation and lung fibrosis is largely unknown." (PMID 35167499, 2022).
lymphangiectasia (1 paper, 2022). "Human pathological tissue samples from patients diagnosed with lymphangiectasia exhibit defective lymphatic basement membrane and nuclear-to-cytoplasmic localization of NFATC1." (PMID 36073544, 2022).
lymphoid tumors (1 paper, 2025). "Particularly intriguing is the discovery of NFATc1 relocating to the nucleus in a minority of lymphoid tumors, potentially reflecting the activation of the NFAT pathway." (PMID 40076009, 2025).
metastatic prostate carcinoma (1 paper, 2019). A carcinoma that arises from the prostate gland and has spread to other anatomic sites. "Thereby, the interplay between PIM kinases and NFATC1 may also provide possibilities for therapeutic interventions against metastatic prostate cancer through combinatory approaches involving PIM-selective kinase inhibitors." (PMID 31730483, 2019).
multiple sclerosis (1 paper, 2022). A progressive autoimmune disorder affecting the central nervous system resulting in demyelination. "The inflammatory response of Th17 cells in a mouse model of multiple sclerosis depended on αvβ3 integrin signaling, and NFATc1 was required to induce the Th17 transcription factor RORγt." (PMID 34986165, 2022).
nephrotic syndrome (1 paper, 2024). A collection of symptoms that include severe edema, proteinuria, and hypoalbuminemia; it is indicative of renal dysfunction. "NFATc1 is the target for calcineurin inhibitors used for treating nephrotic syndrome, serum IFN-γ is increased in nephrotic syndrome, and JAK/STAT signaling is important in FSGS and in recurrence of FSGS following transplantation." (PMID 38127456, 2024).
nonalcoholic fatty liver disease (1 paper, 2025). "For instance, TUDCA can pharmacologically inhibit endoplasmic reticulum (ER) stress responses, overcoming NFATc1 activation and halting the progression from nonalcoholic fatty liver disease (NAFLD) to nonalcoholic steatohepatitis (NASH)." (PMID 40299532, 2025).
Optic neuropathy (1 paper, 2019). "In conclusion, tacrolimus may protect against axon loss in TNF-induced optic neuropathy by inhibiting the CaN/NFATc1 pathway." (PMID 31087207, 2019).
Peri-Implantitis (1 paper, 2025). An inflammatory process with loss of supporting bone in the tissues surrounding functioning DENTAL IMPLANTS. "NFATc1 serves as a crucial regulator of osteoclast differentiation and is involved in regulating the activity of osteoclastic genes such as thrombin receptor activator protein and cathepsin K.33These findings demonstrate the capacity of hUCMSCs in preventing bone resorption in peri-implantitis." (PMID 39510521, 2025).
promyelocytic leukemia (1 paper, 2022). "Upon SUMOylation, NFATc1/C translocates to promyelocytic leukemia nuclear bodies and then interacts with histone deacetylases, leading to the deacetylation of histones, which ultimately suppresses chromatin activation." (PMID 35484132, 2022).
pseudolymphoma (1 paper, 2025). A neoplastic process that resembles a malignant lymphoma, but has a benign course. "Nuclear staining for nuclear factor of activated T-cells c1 (NFATc1), which had been suggested to be useful in distinguishing PCSM-LPD from pseudolymphoma, was negative in our case." (PMID 40370866, 2025).
pulmonary artery hypertension (1 paper, 2021). "The cell-type specific transcription factor NFATc1 (Nuclear factor of activated T-cells, cytoplasmic 1) promotes TRIB3 expression in vascular smooth muscle cells upon phenamil treatment resulting in an attenuation of pulmonary artery hypertension in rats." (PMID 33920424, 2021).
pulmonary TB (1 paper, 2023). "Our study identified unique gene signatures (IL-27, STAT1, IRF1, TLR4, IL-15, IL-2RA, IL-24, TGFβ, CD28, CD80, NFATC1, and PTGDR2) that discriminate active pulmonary TB from uninfected controls using unstimulated PBMCs." (PMID 37460564, 2023).
renal osteodystrophy (1 paper, 2020). Abnormalities of bone mineral metabolism associated with chronic kidney disease. "The IS/AhR/NFATc1 pathway prevents the CKD-associated deterioration of bone metabolism, and therefore, AhR antagonists may serve as novel drugs for renal osteodystrophy." (PMID 32429048, 2020).
sebaceous tumours (1 paper, 2015). "In addition, expression of bulge SC marker molecules, including NFATc1, K15 and CD34 were decreased in sebaceous tumours." (PMID 25608467, 2015).
squamous cell carcinoma (1 paper, 2022). A carcinoma arising from squamous epithelial cells. "Nevertheless, NFATc1 has been reported to increase differentiation of keratinocytes, and immunosuppressant calcineurin inhibitor drugs such as cyclosporin have been proposed to induce squamous cell carcinomas in patients at least partially via their inhibitory effects on NFATc1." (PMID 36190982, 2022).
synucleinopathies (1 paper, 2025). "We recently demonstrated that leucine-rich repeat kinase 2 (LRRK2) and nuclear factor of activated T cells 1 (NFAT1) modulate the neurotoxic inflammation in synucleinopathies mediated by microglia." (PMID 41258081, 2025).
thymic carcinoma (1 paper, 2023). Thymic carcinoma (TC) is a type of thymic epithelial neoplasm characterized by a high malignant potential. "When exploring the possible regulators of CD5 expression in thymic carcinomas, we identified NFATC1 upregulation in the tumor." (PMID 38201543, 2023). "When exploring the possible regulators of this phenotype, we discovered that HDAC9 and NFATC1 were characteristically expressed in the neuroendocrine group in adult TECs and thymic carcinomas." (PMID 38201543, 2023). "As a result, further in vitro and in vivo studies are necessary to validate our findings, particularly those related to the activation of HDAC9 and NFATC1 in thymic carcinomas, before they can be applied in a clinical context." (PMID 38201543, 2023). "HDAC9 and NFATC1, which were characteristically expressed in the neuroendocrine group in adult TECs and thymic carcinomas, should be investigated further due to their potential biological significance in TECs and their possibility of being therapeutic targets of thymic carcinomas." (PMID 38201543, 2023). "Therefore, we investigated the correlation between methylation and mRNA expression status in the genes newly identified as activated or suppressed in thymic carcinomas, specifically HIPK2, HDAC9, NFATC1, PAX9, and SIX1 (the methylation status of FEZF2 was not available in the dataset)." (PMID 38201543, 2023).
vascular neoplasm (1 paper, 2025). A benign, intermediate, or malignant neoplasm arising from vascular tissue including arteries, veins, venous sinuses, lymphatic vessels, arterioles and capillaries. "Thus far, vascular tumors harboring an NFATC1/C2 fusion have only been documented in bone and occasionally soft tissue." (PMID 40037835, 2025).
ventricular septal defect (1 paper, 2012). The presence of a defect (opening) in the septum that separates the two ventricles of the heart. "We have previously shown that a tandem repeat in the intronic region of NFATC1 is associated with ventricular septal defects." (PMID 23226213, 2012). "We have previously shown that a tandem repeat in the intronic region of NFATC1 is associated with ventricular septal defects but with no valvular phenotype." (PMID 23226213, 2012).
vitamin A deficiency (1 paper, 2016). Deficiency of vitamin A due to malnutrition, malabsorption, or dietary lack. "NFATc1 has been implicated in this process and NFATc1 expression in B1 B cells has been observed to be effected with vitamin A deficiency." (PMID 28066447, 2016).